CDK12 (cyclin dependent kinase 12)
Diseases named in the same sentence as CDK12 in open-access papers (continued):
Sharing a sentence is not in itself a finding about the gene and the disease.
cancer (continued). "Furthermore, recent studies have highlighted the critical role of CDK12 in human cancer development (28, –, 31)." (PMID 39601580, 2025). "Notably, active CDK12 also suppresses reductive carboxylation, a glutamine-dependent pathway critical for lipid synthesis and cancer proliferation." (PMID 40996961, 2025). "We next evaluated the predictive value of CDK12/13 expression in a pan-cancer setting." (PMID 40955658, 2025). "In this work, we have predominantly focused on the basic molecular mechanisms regulating RNA Pol II, but it has not escaped our notion that these discoveries open direct avenues to actionable synthetic (inactivation of the CDK12-gene in specific cancers) and combinatorial lethalities." (PMID 40186208, 2025). "Additionally, several other companies are developing CDK12/13 inhibitors, underscoring the substantial therapeutic potential of targeting these kinases for cancer treatment." (PMID 40955658, 2025). "Although the role of CDK12 in cancer has been broadly investigated, its specific role in oocyte development is unknown." (PMID 40148269, 2025). "Thus, since the role of CDK12/13 in cancer is outside the scope of this review, we refer to excellent reviews on the topic." (PMID 39533070, 2025). "Emerging evidence suggests a significant involvement of CDK12 in various cancers." (PMID 39353441, 2024). "Therefore, a comprehensive and in-depth analysis of the correlation between CDK12 and cancer will provide new strategies for cancer management and treatment." (PMID 38503865, 2024). "Early surveillance and employment of CDK12 inhibitors, along with concomitant immunotherapy interventions, may enhance the clinical outcomes of cancer patients." (PMID 38503865, 2024). "In addition, PFS data showed that the low expression of CDK12 in ESCA and KIRC was associated with poor prognosis, while the opposite was true in the other four cancers." (PMID 38503865, 2024). "In this study, we found that early monitoring of CDK12 expression could assist in diagnosing multiple types of cancer and predicting poor prognosis." (PMID 38503865, 2024). "Moreover, the relative expression level of CDK12 in different cancer cell lines from the CCLE database was ranked from high to low." (PMID 38503865, 2024). "In our study, we identified new cancer types that were strongly related to CDK12." (PMID 38503865, 2024). "However, CDK12 was a low-risk factor in KIRC and READ but a high-risk factor in other cancers, especially KICH, with an HR of 9.442." (PMID 38503865, 2024). "Thus far, down-regulation of CDK12-dependent HR genes is being explored as an approach to eliminate cancer cells, most notably in combination with PARP1 inhibitors or DNA-damaging chemotherapeutics." (PMID 37811895, 2023). "Given that for years, mitosis has been viewed as a promising cancer target, targeting Cyclin K or CDK12 may provide an alternative strategy for mitotic-based anti-cancer therapy." (PMID 37626854, 2023). "CDK12/13 inhibitors have been demonstrated to inhibit cancer cell growth." (PMID 37190191, 2023). "Increasing evidence demonstrate the involvement of CDK12 in cancer." (PMID 38104154, 2023). "Our work offers fresh avenues for combinatorial targeting of CDK12 in cancer." (PMID 37811895, 2023). "Moreover, transcriptomic analyses of the effects of CDK12/13 inhibition highlighted new potential vulnerabilities of HGSOC to drugs that are clinically approved for other cancer types." (PMID 37202753, 2023). "Consequently, small-molecule inhibitors targeting CDK12 are of great interest as potential targeted cancer therapies." (PMID 37205756, 2023). "However, our results call for therapeutic exploitation of novel vulnerabilities and resistance mechanisms that arise in response to gene induction in CDK12-inhibited cancer cells." (PMID 37811895, 2023).
cancer (continued). "Consequently, small-molecule inhibitors targeting CDK12 are of great interest for cancer treatments as potential targeted therapies." (PMID 37205756, 2023). "In principle, the induced genes could elicit novel vulnerabilities and/or resistance mechanisms of CDK12-targeted cancer cells." (PMID 37811895, 2023). "Availability of a novel CDK12 inhibitor AU-15506 (Aurigene Discovery Technologies Ltd.)allowed us to test if this compound can inhibit receptor activity or intracellular kinases and therefore has potential anti-cancer activity." (PMID 37190191, 2023). "Moreover, our study indicates that CDK12/13 inhibition enhances the efficacy of approved drugs that are already in use for HGSOC or other human cancers." (PMID 37202753, 2023). "Therefore, we concluded that AU15606 and AU-16770 are CDK12/13-specific highly potent anti-cancer agents in vitro." (PMID 37190191, 2023). "Several CDK12 inhibitors have been shown to have potential for cancer therapy." (PMID 38104154, 2023). "We went on to test the CDK12-d model across other cancer types." (PMID 36883553, 2023). "Given our findings gathered thus far, we hypothesized that selective targeting of CDK12 renders cancer cells highly dependent on P-TEFb." (PMID 37811895, 2023). "If there was a clinical trial indication at level C or D for a specific cancer type, such as amplification of MDM2 or FGFR1 or mutations of AKT1, ATM, CDK12, and PTEN, patients were considered as candidates for receiving treatment, although in most cases, no clinical trials were available." (PMID 36251535, 2023). "Therefore, we provide a rationale for combinatorial targeting of CDK12 with either P-TEFb or oncogenic signaling pathways in cancer." (PMID 37811895, 2023). "CDK12 function and its role as a target for cancer treatment has been reviewed recently." (PMID 37190191, 2023). "Therefore, future exploration of processes driven by perturbation of CDK12 shall reveal the full potential of therapeutic targeting of this crucial Pol II elongation kinase in cancer." (PMID 37811895, 2023). "As elimination of cancer cell by irreversible cell death is a desirable outcome of any effective cancer treatment, we examined whether the targeting of CDK12 or P-TEFb switches the fate of CDK7-inhibited cells from cell-cycle arrest to apoptosis." (PMID 37811895, 2023). "Pan‐cancer data regarding the frequency of CDK12 alterations is limited." (PMID 34898046, 2022). "CDK12 alterations have generated recent interest as a potential biomarker for cancer response." (PMID 34898046, 2022). "No linkage between CHD1 and CDK12 mutations and cancer progression has been observed in our cohort except for the germline variant P1275L in CDK12 that will be discussed later." (PMID 35347810, 2022). "As both pathways are involved in cancer cell growth, survival and proliferation, these results suggested that they might promote resistance to CDK12 inhibitors." (PMID 36309522, 2022). "Together, these types of observations could be interpreted that in some proportion of cancer cell lines, CDK12 and AFF3 may have synergistic effects on cell proliferation and survival, potentially affording synthetic lethal opportunities." (PMID 36577800, 2022). "Genomic alterations in the CDK12 gene have been detected in breast, ovarian, and prostate cancers." (PMID 36309522, 2022). "However, some limitations are present due to the inherent nature of a retrospective pan‐cancer analysis and our relatively small sample of patients with CDK12‐altered tumors which prevents more robust conclusions." (PMID 34898046, 2022).
cancer (continued). "Pan‐cancer data regarding the frequency of CDK12 alterations are limited." (PMID 34898046, 2022). "However, there are limited pan‐cancer data regarding the frequency of CDK12 alterations, especially in the context of patients with or without metastases." (PMID 34898046, 2022). "Based on these findings, we reasoned that the profound metabolic adaptations induced by CDK12 overexpression are typical of those enacted by rapidly proliferating cancer cells to meet their increased bioenergetic demand and requirement for nucleotide synthesis." (PMID 35550508, 2022). "By comparing focal SCNAs in matched NSCLC-BM pairs, we identified putative BM-driving alterations affecting multiple cancer genes, including several potentially targetable alterations in genes such as CDK12, DDR2, ERBB2, and NTRK1, which we validated in an independent cohort of 84 BM samples." (PMID 36561283, 2022). "Pan‐cancer studies evaluating the prevalence of CDK12 alterations have been limited." (PMID 34898046, 2022). "There is a growing body of evidence suggesting that other cyclin-dependent kinases including CDK7, CDK8, CDK9, and CDK12 may also be important for modulating the sensitivity of cancer cells to the effects of ionizing radiation." (PMID 34932500, 2022). "CDK12 altered tumors represent a clinically distinct molecular cancer subtype which may have increased responsiveness to checkpoint inhibition." (PMID 34898046, 2022). "Several CDK12 inhibitors and their anti-cancer activities have been reported." (PMID 36145262, 2022). "Thus, CDK7 and CDK12/13 inhibitors likely modulate similar biological processes through different mechanisms, suggesting possible synergistic anti‐cancer effects on their combined administration." (PMID 34092037, 2021). "CDK9 and CDK12/13 inhibitors are currently tested for their efficiency to kill cancer cells." (PMID 34663829, 2021). "Although how the cell cycle checkpoint was regulated by these potential proteins has remained unclear, one point should be noticed: the inhibitor of CDK12/CDK13 might be a promising option for some types of cancer." (PMID 34513922, 2021). "This suggests that CDK12 gene amplification contributes to the pathogenesis of cancer." (PMID 32489449, 2020). "CDK12 inhibitors have the potential to be useful in the applicationof SL to cancer therapy." (PMID 33135887, 2020). "Moreover, the inhibition of CDK12 emerges as a promising strategy for treatment in several types of cancers." (PMID 34316683, 2020). "The CCK8 assay results demonstrated that CDK12 downregulation inhibited cancer cell proliferation." (PMID 32489449, 2020). "In metastatic osteosarcoma (OS), a cancer with a high degree of genome instability, treatment with several CDK12 inhibitors led to the sensitivity of OS cell lines and a decrease in metastatic cell outgrowth in the lungs, perhaps partly due to the defective expression of DNA damage response genes." (PMID 34316683, 2020). "In conclusion, CDK12 promotes cancer metastasis in vivo and in vitro." (PMID 32489449, 2020). "Studying the effectivityand safety of abemacicliband atezolizumab in participants with metastatic castration-resistantprostate cancer with and without “CDK12 loss” mutation." (PMID 33135887, 2020). "Therefore, we conducted a transwell assay and metastasis assay in vivo to study the mechanism of CDK12 in cancer metastasis." (PMID 32489449, 2020). "Inhibition of CDK12 is considered a favorable strategy for cancer treatment." (PMID 32570740, 2020). "Taken together, targeting CDK12 may be a viable treatment strategy for cancers driven by dysregulated transcription factors." (PMID 32570740, 2020). "Several studies have shown that inhibiting CDK12 can sensitize cancer cells to PARP inhibitors." (PMID 32804079, 2020).
cancer (continued). "Therefore, we now consider CDK12 an upstream factor in the BRCA and HR gene response pathway, and CDK12 mutations, as well as BRCA mutations, can be therapeutically used to predict the sensitivity to PARP inhibitors in cancer treatment." (PMID 32451425, 2020). "Here, we discuss the diverse roles of CDK12 in gene expression regulation and human cancer, focusing on newly identified CDK12 kinase functions in cellular processes and highlighting CDK12 as a promising therapeutic target for human cancer treatment." (PMID 32451425, 2020). "Transwell assays and in vivo metastasis models were used to observe whether CDK12 can promote cancer metastasis." (PMID 32489449, 2020). "The potential of CDK12 as a major therapeutic anti-cancer target is gradually being discovered." (PMID 34316683, 2020). "Recently, more and more evidence demonstrates the involvement of CDK12 in cancer." (PMID 32570740, 2020). "In this circumstance, cancers might depend on CDK12 activity for cell proliferation, and its inhibition may result in cancer-specific cell death." (PMID 32451425, 2020). "CDK12 can activate and modulate cancer-related gene expression, but, according to a review by Seung Hyuk Choi and colleagues at the Salk Institute for Biological Studies in La Jolla, USA, further investigations into its exact functioning and control mechanisms are required." (PMID 32451425, 2020). "Therefore, the previous investigations of biological function of CDK12 in cancer cells were mainly focused on its ability to maintain DNA repair pathways." (PMID 31523177, 2019). "Therefore, RNA processing or transcriptional regulation of downstream effect genes can be one of the mechanisms of CDK12 regulating biological behavior of cancer cells." (PMID 31523177, 2019). "Despite growing knowledge of CDK12 function in cancer cells and the availability of selective CDK12/13 inhibitors, the molecular basis for the selective effects of this kinase on DDR genes remains unclear." (PMID 30988284, 2019). "In the era of precision oncology, inactivation of CDK12 may represent a new molecular subtype with therapeutic implications, although the pan-cancer prevalence of this genomic alteration was previously unknown." (PMID 31360735, 2019). "Nevertheless, whenever dysregulated, CDK12 is overexpressed rather than mutated in vast majority of human cancers, highlighting its important role in promoting cell proliferation." (PMID 29760377, 2018). "They will be instrumental for studying physiological function of CDK12 and could be tested as anti-cancer drugs." (PMID 29090014, 2017). "CDK12 inhibitor monotherapy could be useful for cancer patients tumors with overexpressed and activated CDK12." (PMID 29090014, 2017). "Since CDK12 maintains a dedifferentiated state in mouse embryonic stem cells, one could envision a scenario where CDK12 maintains the dedifferentiated state of cancer stem cells." (PMID 29090014, 2017). "This suggests that certain tumors might be transcriptionally addicted to CDK12 and so CDK12 inhibition might be a promising anti-cancer strategy." (PMID 29090014, 2017). "This study is the first to our knowledge to establish an association between diminished expression of CDK12/13 and heightened STING activity, identifying CDK12/13 expression as a predictive biomarker for ICB response and patient survival in ICB-treated cohorts in a pan-cancer context." (PMID 40955658, 2025). "Therefore, attenuated expression levels of CDK12/13 may lead to the activation of STING signaling in various cancer types." (PMID 40955658, 2025). "As knockdown of TAD anchor non-oncogenes PSMD3 led to activation of its partner boundary oncogene CDK12, RNA mutation of the non-oncogene could be a potential mechanism that underlies cancer driver gene activation." (PMID 40051047, 2025). "We reasoned genes dysregulated in CDK12-mutant cancers might be CDK12 synthetic lethal genes." (PMID 39368479, 2024).
cancer (continued). "Therefore, the inhibition of CDK12 expression can assist in cancer therapy." (PMID 38503865, 2024). "In Case 3, a CDK12 variant was detected in all cells of Regions A and B; whereas, four variants in ATRX, BRCA2, PIK3CA, and PPARG were detected specifically in Region A. All four variants displayed low VAFs (0.05–0.07), indicating a late molecular event present in a small subset of cancer cells." (PMID 39766052, 2024). "Consequently, CDK12-inhibited cancer cells exhibit hypersensitivity to inhibitors of P-TEFb." (PMID 37811895, 2023). "The hereby presented observation that CDK12 regulates PD-L1 mRNA variant expression and helps to dictate the balance of sPD-L1 relative to mPD-L1/exoPD-L1 brings CDK12 and CDK12 inhibitors into a novel immunotherapeutic context with relevance for NSCLC and other cancer types." (PMID 38132164, 2023). "However, published reports have not shown a pan‐cancer connection between CDK12 alterations and homologous recombination deficiency (HRD) phenotype." (PMID 34898046, 2022). "However, the overlap between the MYC and cellular functions of CDK12 indicate that CDK12 could be an effective therapeutic target for MYC-dependent cancers." (PMID 33805800, 2021). "Thus, the differential outcome of CDK12‐inactivation reported in different cancers may actually rely on the same activity of this kinase." (PMID 34092037, 2021). "In this scenario, CDK12 might be a promising therapeutic target for the cancers described." (PMID 32451425, 2020). "Moreover, the role of CDK12 in cancer is contradictory and unclear 14-21." (PMID 32483448, 2020). "It is possible that CDK12 might govern some cancer-specific transcription programs." (PMID 32451425, 2020). "Here we show that CDK12 inhibition in cancer cells lacking CDK12 mutations results in gene length-dependent elongation defects, inducing premature cleavage and polyadenylation (PCPA) and loss of expression of long (>45 kb) genes, a substantial proportion of which participate in the DDR." (PMID 30988284, 2019). "Thus, effects attributed to CDK12 loss do not appear to be restricted to cancers with loss-of-function mutations, but encompass those with severe underlying DNA damage, such as NB." (PMID 30988284, 2019). "The extent to which these observations apply to other genomically unstable cancers lacking CDK12 loss-of-function mutations will be pivotal in generating molecular rationales for the therapeutic targeting of CDK12 across a broad cross-section of vulnerable tumors." (PMID 30988284, 2019). "This idea might be supported by the fact that CDK12 inhibition limits the growth of cancer cells." (PMID 29090014, 2017). "Also, mutant, inactive forms of CDK12 sensitize cancer cells to cisplatin." (PMID 29090014, 2017). "Analogously, cancer cells may depend on CDK12 and thus it can serve as a therapeutic target." (PMID 29090014, 2017). "This review highlights the biological rationale for targeting CDK12 and CDK13 in cancer, summarizes emerging therapeutic strategies, and identifies key opportunities for integrating these approaches into precision oncology." (PMID 41491919, 2026). "Of 21 gene-cancer type pairs with significant interaction effects (FDR<0.05), 14 showed positive interaction effects with the largest effects found in FGFR3 in BLCA, CDK12 in STAD, and MET in LGG." (PMID 41415395, 2025). "Cyclin-dependent kinases 12 and 13 (CDK12/13) have emerged as promising therapeutic targets for castration-resistant prostate cancer (CRPC) and other human cancers." (PMID 40080446, 2025).